CD47 (CD47 molecule)
Diseases named in the same sentence as CD47 in open-access papers (continued):
Sharing a sentence is not in itself a finding about the gene and the disease.
tumor (continued). "In line with enhancing the antitumor effect of anti-CD47 therapy, an oncolytic herpes virus has been generated to avoid infusion toxicities and increase the blood-brain barrier–penetrating efficiency of anti-CD47, which exhibits superior tumor cytotoxicity in GBM." (PMID 36594466, 2023). "The CD47/SIRPα axis requires SHP2 deneddylation to disrupt clearance of tumor cells." (PMID 36626230, 2023). "Such an approach may hold promise in overcoming the limitations and improving the effectiveness of CD47-SIRP-based therapy in the treatment of non-neoplastic diseases." (PMID 38125492, 2023). "Thus, blocking of CD47‐SIRPα binding between tumor cells and innate immune cells can increase phagocytosis of tumor cells." (PMID 36598153, 2023). "In both models, anti-CD47 therapy significantly enhanced the anti-tumor activity of T-DM1." (PMID 37468567, 2023). "CD47 is a key factor mediating immune evasion of tumor cells from the innate immune system." (PMID 37197432, 2023). "CD47 is an essential tumor antigen for the initiation and progression of several cancer types." (PMID 37426676, 2023). "Engineered oncolytic herpes simplex virus encoding CD47 targeting antibodies have been used to disrupt the CD47-SIRPα signaling axis and enhance both macrophage-mediated ADCP and NK cell-mediated ADCC, harnessing the overexpression of the CD47 “don’t eat me” signal on many tumor cells." (PMID 36765035, 2023). "Cancer cells could influence TAM through the interaction between CD47 on tumor cells and the signal regulatory protein (SIRP)α; this pathway generates a “do not eat me signal”, that could protect tumor cells from macrophage-mediated phagocytosis." (PMID 37504315, 2023). "The pyroglutamylation of CD47 on tumor cells is critical for its binding to SIPRα on macrophages." (PMID 37063864, 2023). "Additionally, Cordycepin has been reported to exert anti-tumor effects by promoting apoptosis and autophagy, as well as suppressing CD47 expression to enhance anti-tumor immunity." (PMID 38178862, 2023). "Therefore, blocking the CD47-SIRPα interaction directly improves the macrophages’ ability to clear tumor cells, senescent red blood cells, and platelets, leading to adverse reactions." (PMID 37484024, 2023). "Interestingly, both PD‐L1 and CD47 are highly expressed in tumour cells and can be synchronously regulated by transcription factor MYC." (PMID 37974395, 2023). "SENP8 regulates deneddylation in TIMs to respond to tumor cell CD47." (PMID 36626230, 2023). "Finally, anti-CD47 antibodies can stimulate tumor cell apoptosis through a caspase-independent mechanism." (PMID 37373873, 2023). "Hence, we evaluated the effects of diHEP-DPA and 5-FU on SIRPα and CD47 expression in tumor tissues." (PMID 36827121, 2023). "In vivo, CD47 blockade results in significant pro-inflammatory polarization of macrophages in mice xenografted with human glioblastoma and enhanced phagocytosis of tumor cells." (PMID 37143666, 2023). "CD47 is an immunosuppressive molecule that binds SIRPα on antigen-presenting cells to regulate an innate immune checkpoint that blocks phagocytosis and subsequent activation of adaptive tumor immunity." (PMID 37958404, 2023). "The disruption of the CD47/SIRPα axis reduces the ability of the tumor to escape phagocytosis." (PMID 36827121, 2023). "Overexpression of CD47 allows tumour cells to evade phagocytosis." (PMID 36900335, 2023). "Similarly, CAR-T cells secreting nanobodies targeting the prominent “don’t eat me” signal CD47 induced enhanced infiltration and activation of macrophages in the tumor with limited systemic toxicity." (PMID 36167831, 2023). "We then explored the affinity of fusion HAC NVs and their ligands PD‐L1 and CD47 on tumour cells." (PMID 37974395, 2023). "Therefore, imiquimod-encapsulated liposomes coupled to Fc-CV1 seem to be a promising novel nanomedicine to improve CD47 expression tumor treatment." (PMID 37049910, 2023).
tumor (continued). "Differences in the findings across these correlative NSCLC studies may reflect disparate patient or tumor characteristics in the individual cohorts, antibody-staining conditions, or differences in thresholds used for scoring CD47 positivity." (PMID 37958404, 2023). "This may be due to increased expression of CD47, an anti-phagocytotic surface protein, on tumor cells." (PMID 36768342, 2023). "The tumor growth-inhibitory effect of the anti-CD47 antibody was similar to that of 5-Fu." (PMID 36860925, 2023). "Indeed, CD47 KO in A549 cells attenuated IFNγ-stimulated invasion and migration in vitro and tumor metastasis in mice." (PMID 37958404, 2023). "Collectively, our findings suggested that the combination treatment of cordycepin and the anti-CD47 antibody could significantly enhance tumor suppression, increase the proportion of M1 macrophages, and decrease the proportion of M2 macrophages." (PMID 37138855, 2023). "CD47 is a “don’t eat me” signal, and blocking CD47/SIRP enhances TAM phagocytosis of tumor cells." (PMID 37781367, 2023). "Interestingly, anti-O-acetyl-GD2 antibody therapy enhanced CD47 expression on tumor cells and induced influx of F4/80+ macrophages in a NXS2 liver metastasis model, which further explains the synergy of anti-GD2 and anti-CD47 therapy." (PMID 38087370, 2023). "Moreover, the anti-tumor functions of macrophages can be enhanced through nanobody-mediated blockade of the CD47/SIRPa pathway, reprogramming of macrophages from M2 to M1 phenotype and depletion of TAMs from the TME." (PMID 36761751, 2023). "This may be due to the low potency of those agents in increasing apoptosis, in addition to concerns for decreased selectivity to tumor cells, as CD47 are expressed on normal tissue cells as well." (PMID 38001669, 2023). "Hence, there is considerable interest in targeting CD47 and its associated signals as a therapeutic strategy; for example, blocking CD47 was found to significantly inhibit tumor growth and metastasis." (PMID 36823373, 2023). "CD47 is frequently overexpressed in tumors and promotes tumor cell immune evasion." (PMID 37541303, 2023). "Afatinib or anti‐CD47 antibody treatment alone inhibited tumor growth and prolonged mouse survival." (PMID 37541303, 2023). "Of note, CD47 was also highly expressed in non-tumor brain tissue." (PMID 36825029, 2023). "The effect of the CD47-SIRPα axis on the proliferation and survival of tumor cells is indirect." (PMID 37484024, 2023). "CD47 (don’t eat me signal) is a crucial molecule expressed by tumors that impedes macrophage recognition of the tumoral cells, which results in a decreased phagocytosis and in tumor evasion." (PMID 37284199, 2023). "Combined anti-CD47 immunotherapy can synergistically inhibit tumor growth and recurrence by increasing the efficiency of tumor infiltration by M1 macrophages and cytotoxic CD3+ and CD8+ T cells while decreasing the efficiency of immunosuppressive regulatory T cells." (PMID 37168380, 2023). "Hence, these data suggest that CD47-SIRPα represents a new tumor escape mechanism that in addition to its ability to inhibit innate immunity also acts to restrain the adaptive immune response." (PMID 36882648, 2023). "Furthermore, inhibition of CD47 by anti-CD47 antibodies was shown to effectively target pancreatic CSCs by increasing macrophage-mediated immunity and tumor cell apoptosis." (PMID 36900399, 2023). "CD47-targeted therapies may also work synergistically with other immunotherapies, such as checkpoint inhibitors, to further enhance anti-tumor immunity and improve clinical outcomes." (PMID 38188674, 2023). "CD47–SIRPα axis is the first tumor phagocytosis checkpoint pathway identified in the late 2000s." (PMID 36939440, 2023). "Tumor cells often overexpress immune checkpoint proteins, including CD47, for immune evasion." (PMID 37541303, 2023).
tumor (continued). "Therefore, CD47 overexpression in tumor cells results in the inhibition of phagocytosis by tumor‐associated macrophages (TAM) and is crucial for the survival and proliferation of tumor cells as well as metastasis of hematopoietic malignancies and solid tumors." (PMID 37698048, 2023). "In addition, significant increases in IFN-γ+ CD8+T-cells and CD4+ T-cells populations within tumor-infiltrating lymphocytes (TIL) were observed after MyxV_CD47/IFN-γ treatment." (PMID 37835397, 2023). "Therefore, SIRPα inhibitors, such as CD47 analogues or anti-SIRPα antibodies, are proposed as therapeutic agents that promote the phagocytosis of tumor cells by macrophages." (PMID 37999184, 2023). "Considering CAR T cells traffic to and expand at tumor site, local delivery of anti-CD47 scFv could potentially abate the toxicity of systemic CD47 blockade, which was manifested in our in vivo experiments." (PMID 37781520, 2023). "Most simply, CD47 blockade could be administered intratumorally, an approach that impaired the growth of subcutaneous tumor models." (PMID 37958404, 2023). "This phenotype was recapitulated in LK-2 tumors that developed in Rag2–/–Il2rg–/–Cd47–/– recipient mice, where a significantly higher proportion of parental LK-2 than CALB1-deficient LK-2 2B7 tumor cells stained positive for p63, a marker for squamous epithelial differentiation encoded by TP63." (PMID 37192000, 2023). "One essential and well-studied function of CD47 related to tumor development is preventing phagocytosis via ligating with signal regulatory protein-alpha (SIRPα) on the surrounding phagocytes and evading destruction by using the innate and adaptive immune system." (PMID 37063284, 2023). "As Raji-luc cells expressing very low level of hPD-L1, the anti-CD47 arm of 6MW3211 may play a critical role in anti-tumor activity in this Raji-luc xenograft model." (PMID 36593962, 2023). "The combination of the low-dose anti-CD47 antibody with the MSLN-CAR-iMACs could inhibit tumor growth to some extent." (PMID 37723178, 2023). "Furthermore, combining cGAMP with the antagonistic anti-CD47 mAb increases the phagocytic clearance of tumor cells and induces systemic anti-tumor immune responses, which depends on STING and type I IFN signaling." (PMID 37380989, 2023). "One approach is to combine CD47-targeted therapies with other immune checkpoint inhibitors, such as anti-PD-1/PD-L1 antibodies, to overcome the immune evasion mechanisms employed by tumor cells." (PMID 38188674, 2023). "Though blockade of CD47/SIRPα signaling promoted macrophages phagocytosing tumor-originated mitochondrial DNA (mtDNA), it inhibited the phonological function of DCs which can reduce mtDNA degradation in DCs and activate DCs’ anti-tumor function by inducing type I interferon." (PMID 36845095, 2023). "It has been reported that tumor cells co-cultured with macrophages under the intervention of anti-CD47 antibody could promote the tumor recognition and phagocytosis of macrophages." (PMID 37171006, 2023). "Apart from enhancing macrophage phagocytosis of tumor cells, blocking CD47 may also increase macrophage recruitment to tumor cells." (PMID 37719086, 2023). "Furthermore, macrophage removal reversed tumor development following CD47 blockage, demonstrating that macrophages are essential for suppressing the proliferation of cancer cells after CD47 dampening." (PMID 38033495, 2023). "CD47 can bind to SIRPα on the surface of macrophages to convey the “don’t eat me” signal to macrophages, forming the antiphagocytic signaling axis, inhibiting phagocytosis of macrophages on tumor cells." (PMID 36911723, 2023). "Additionally, it enhanced T cell infiltration and increased the possibility of releasing innate and adaptive anti-tumor responses through CD47-targeted therapy." (PMID 38093355, 2023). "Anti-CD47 showed potent anti-tumor activity and synergized with PARPi in OC models." (PMID 37468567, 2023).
tumor (continued). "We hypothesize that by providing an "eat me" signal and blocking the "don't eat me" signal, through ICD inducer and blocking CD47 respectively, DCs and macrophages would phagocyte tumor cells and induces an immune response." (PMID 36774400, 2023). "Additionally, the use of antibodies against CD47 and PD-L1 was shown to exert synergistic anti-tumor immunity effects." (PMID 38258072, 2023). "CD47 blockade inhibits tumour growth in mouse heterotopic and orthotopic models of HCC." (PMID 37894344, 2023). "Therefore, MYC can promote tumor progression directly as well as give rise to tumor immunosuppression, which can indirectly result in tumor progression by regulating CD47 and PD-L1." (PMID 37221625, 2023). "CD47 is often overexpressed on tumor cells and binds to SIRP-α expressed on macrophages to deliver the “don’t eat me” signal to macrophages, which ultimately results in the evasion of immune surveillance; this phenomenon has been correlated with poor prognosis." (PMID 37313405, 2023). "CD47 acting as a “don't eat me” signal to macrophages can trigger tumor immune escape." (PMID 37171006, 2023). "Additionally, it has been reported that anti-CD47 antibody-mediated phagocytosis of tumor cells through macrophages can induce cytotoxic CD8+ antitumor T-cell reactions in mice." (PMID 37291116, 2023). "A total of 29/98 patients (29.6%) expressed some level of CD47 in the tumor tissue; however, it was not possible to associate the expression with disease-specific overall survival." (PMID 37569332, 2023). "Thus, mutant KRAS communicates with macrophages via the CD47/SIRPα axis and renders tumor cells insensitive to phagocytosis by macrophages." (PMID 36413402, 2023). "Instead, the downregulation of the antiphagocytic CD47 “don’t eat me” signal on tumor cells was deterministic for phagocytosis by macrophages, and thus the measurement of this biomarker could be implemented in a future readout." (PMID 36672243, 2023). "Several studies have attempted to improve the tumor selectivity of anti-CD47 agents by generating bispecific antibodies (i.e., an antibody which recognizes two different antigens on tumor cells simultaneously), which have been demonstrated to minimize side effects." (PMID 36650558, 2023). "In addition to inhibiting binding between CD47 and SIRPα, antibodies targeting CD47 have the potential added benefit of blocking tumor-promoting cell-intrinsic CD47 signaling, but at the cost of challenges associated with the CD47 antigen sink." (PMID 37958404, 2023). "2C8 has high specificity and affinity of CD47 protein and suppresses tumor growth." (PMID 36721212, 2023). "Interestingly, the development of an in situ tumor vaccine expressing anti-CD47 antibodies resulted in tumor growth suppression, stronger long-term survival, and increased tumor-infiltrating lymphocytes in melanoma, lymphoma, and breast cancer mouse models." (PMID 37443821, 2023). "Notably, we demonstrated the co-expression of CD47 and PD-L1 on several tumor tissues using mIHC technology." (PMID 36593962, 2023). "Inhibition of the CD47/SIRPα axis can reduce tumor size and metastasis in many tumor models." (PMID 36960057, 2023). "We hypothesized that Kaiso is involved in immune evasion and thereby in tumor growth by modulating the THBS1/CD47/SIRPA axis." (PMID 37190208, 2023). "Moreover, CD47-SIRPα blockade can result in increased anti-tumor activities and enhanced macrophage phagocytosis of the tumor cells." (PMID 36721212, 2023). "Although CD47 blockade has a good prospect as anti-tumor medicine, there are issues to be solved." (PMID 37345054, 2023). "In this study, Abrine and anti-PD-1 antibody were used to treat Hepa1-6 xenograft mice, results showed that both inhibited the expression of CD47 and PD-L1 in tumor tissues of mice, increased the levels of CD4+ and CD8+ T cells, decreased the level of Foxp3+ Treg cells." (PMID 37334368, 2023).
tumor (continued). "Moreover, AsiC mixtures can be easily created from the assembly of individual AsiCs, and the combination of the four most effective EpCAM-AsiCs (targeting Upf2, Parp1, Cd47, and Mcl1) exerted a better tumor inhibition effect than the individual EpCAM-AsiCs." (PMID 36969696, 2023). "However, antibodies can only bind to tumor cells which express human CD47 in these immunocompromised xenograft models." (PMID 36650558, 2023). "However, ICD inducers can also induce the expression of inhibitory checkpoint receptors CD47 and PD-L1 on tumor cells, making CRC tumors resistant to mainly CD8 T cell killing and macrophage-mediated phagocytosis." (PMID 36774400, 2023). "The CD47 gene displayed high expression levels across the four subgroups and the non-tumor tissue." (PMID 36825029, 2023). "Since hematological malignancies, including MM, express high CD47 levels, preclinical research demonstrated that an antibody-mediated blockade of CD47-SIRPα signaling could promote tumor cell death, phagocytosis and improve T-cell response." (PMID 37504315, 2023). "Our study aimed at inhibiting the expression of CD47 gene in the tumor cells to reduce immune escape, activating antigen-presenting cells (APCs), and eliminating the tumor immunosuppressive microenvironment through the construction of siCD47 and R848-loaded nanoparticles." (PMID 37063284, 2023). "Our fusion HAC NVs could effectively block both PD‐L1 and CD47 checkpoints on tumour cells to elicit antitumour immunity of T cell and macrophage respectively." (PMID 37974395, 2023). "Finally, in vivo experiments showed that anti-CD47 antibody (B6H12 or MIAP301) significantly inhibited the tumor growth and this effect of inhibition was partly blocked by the depletion of macrophages." (PMID 37171006, 2023). "However, numerous studies indicate that administration of agents that block the CD47/SIRPα phagocytosis checkpoint leads to improved tumor clearance in vivo." (PMID 36787255, 2023). "Deciphering malignancy-specific mechanisms influencing the efficacy of CD47 blockade may also nominate proteins that regulate tumor sensitivity and resistance as response-predictive biomarkers." (PMID 37958404, 2023). "Additionally, CD47 shields tumor cells from macrophage phagocytosis, and high levels of CD47 expression correlate with a poor prognosis in several types of cancer." (PMID 36903458, 2023). "Thus, the gene expression and drug release behavior of tumor-homing bacteria can be spatiotemporally manipulated in vivo by a magnetic field, achieving tumor-specific CD47 blockage and precision tumor immunotherapy." (PMID 36959204, 2023). "Although low CD47-expressing cancer cells still allow phagocytosis, the reverse signaling delays the process, leading to incomplete digestion of the entrapped cells and subsequent tumor hybrid cell (THC) formation." (PMID 37848444, 2023). "We speculate that BC31M4 promoted the phagocytosis of tumor cells through blocking the CD47-SIRPα interaction and engaging the activating FcγRs on phagocytes, after which such phagocytes may be activated to prime T cell immunity and to induce immune memory." (PMID 36650558, 2023). "Our study illustrates that the development of a tumor-selective, pH-dependent anti-CD47 antibody safely confers strong therapeutic effects against solid tumors, thus providing a promising therapeutic strategy to overcome the challenges of anti-CD47 therapy." (PMID 36650558, 2023). "Magrolimab is an anti-CD47 antibody that promotes phagocytosis of lymphoma cells in preclinical models, polarizes macrophages from a tumor-tolerant M2 phenotype to an anti-tumor M1 phenotype, and has demonstrated synergy with rituximab in B-cell non-Hodgkin lymphomas." (PMID 37760478, 2023). "Studies have also demonstrated that blocking CD47 can reduce tumor load." (PMID 37719086, 2023). "Furthermore, we were able to further increase the anti-tumor response by blocking both the CD47/SIRPα axis and the sialic acid/Siglec axis." (PMID 37444515, 2023).